IL6 (interleukin 6)
Diseases named in the same sentence as IL6 in open-access papers (continued):
Sharing a sentence is not in itself a finding about the gene and the disease.
apical periodontitis (16 papers, 2020 to 2025). "Similarly, IL-6 is a pro-inflammatory mediator that has been implicated in apical periodontitis with levels directly proportional the sizes of the osteolytic lesions in both animal models and human tissues." (PMID 35639178, 2022). "Studies in patients showed that IL-6 is expressed in apical periodontitis, where its levels correlate to the size of the periapical lesions." (PMID 39253090, 2024). "Multiple studies have investigated the polymorphisms of various ILs, including IL-1α, IL-1β, IL-6, TNF-α, IL-8, IL-10, and IL-12, and their association with the occurrence of apical periodontitis." (PMID 39723289, 2024). "Cytokines such as IL-1α, IL-1β, IL-6, IL-8, and IL-12p40 play significant roles in the development of apical periodontitis." (PMID 39723289, 2024). "In humans, higher levels of IL-6 were significantly found in symptomatic apical periodontitis compared with asymptomatic apical periodontitis, representing an active process immunologically." (PMID 36599453, 2023). "In the mechanism of apical periodontitis, cytokines are involved, including IL-6 and TNF-a for bone resorption, osteoclast activity, and proinflammatory cytokines." (PMID 36599453, 2023). "Enhanced CRP synthesis, in response to IL-6 in apical periodontitis, can act as a potential reservoir of IL-6 and CRP for sustaining a low systemic inflammatory response, thus increasing the risk for atherosclerotic cardiovascular disease." (PMID 35888650, 2022). "In addition, patients with severe forms of apical periodontitis (grades 2 & 3) showed a significant increase in the levels Il-6 in comparison to grade 1 apical periodontitis." (PMID 40097880, 2025). "Notably in the cases of apical periodontitis and pulp necrosis,biomarkers like Interleukin-6 (IL-6) and Interleukin-10 (IL-10) might be employed in endodontics to direct endodontic therapy andevaluate inflammation that occurs in pulpal infections." (PMID 40230914, 2024). "Combined with the histological results and immunohistochemical staining of TNF-α and IL-6 in the periapical area, we proved that the passive ultrasonic irrigation and EASYDO ACTIVATOR treatments could reduce the levels of TNF-α and IL-6, thereby reducing bone destruction in apical periodontitis." (PMID 36053353, 2022). "Several studies have confirmed the pro-inflammatory nature of periapical granulomas, noting higher levels of IL-1β, IL-6, TNF-α, and IL-17 in patients with symptomatic apical periodontitis compared to those with asymptomatic cases." (PMID 39723289, 2024). "The cells more predominant in apical periodontitis are IL-1 α, TNF-α, or IL-6, which activate the osteoclasts (involved in the bone resorption or destruction) and fibroblasts." (PMID 38893626, 2024). "A recent study on apical periodontitis found that FSH aggravated inflammation by enhancing the expression of IL-1 β, IL-6, TNF and Toll-like receptor 4 in human periodontal ligament cells." (PMID 35527996, 2022). "A previous histological study reported increased IL-6 and CRP messenger RNA levels in periodontal ligament tissue of teeth with apical periodontitis." (PMID 35888650, 2022).
atrophic gastritis (16 papers, 2012 to 2025). "Even in the multiple linear regression analysis adjusting for sex, age, and atrophic gastritis, a higher log10-transformed serum IL-6 level was significantly associated with a higher log10-transformed serum anti-H." (PMID 24453409, 2013). "As proinflammatory cytokines involved in atrophic gastritis, IL-6 and IL-11 cause an inflammatory response in the stomach and play important roles in angiogenesis and cell proliferation during the progression of neoplasia; thus, they are used as biomarkers of aggressive tumors." (PMID 26839577, 2016). "Mechanistically, P. gingivalis gingipains and LPS–TLR4 signaling amplify IL-6/IL-17-driven inflammation, creating a pro-inflammatory niche that sustains H. pylori persistence and accelerates gastric atrophy." (PMID 41583463, 2025). "This was further substantiated through analysis of another publicly available dataset (GSE191275), which indicates a significantly higher IL-6 expression in GC tissues (n=10) compared to non-atrophic gastritis (NAG, n=10) and intestinal metaplasia (IM, n=10) (P ≤ 0.0001)." (PMID 38422751, 2024). "However, consistent with previous reports, IL-1RT1 signaling is required for IL-6 expression during STAT3 induced gastric atrophy." (PMID 25528766, 2015). "Furthermore, serum IL-6 levels were significantly associated with H. pylori IgG levels independent of sex, age, and atrophic gastritis stage." (PMID 24453409, 2013). "Consequently, CagA-induced proinflammatory cytokines, interleukin (IL)-1, IL-6, IL-18, tumor necrosis factor α (TNFα), and interferon-γ (IFN-γ), will increase, triggering gastric mucosa inflammation and atrophic gastritis." (PMID 38276136, 2024). "Thus, the possible elevation of serum IL-6 due to H. pylori infection was not determined by the level of atrophic gastritis." (PMID 24453409, 2013).
bacterial vaginosis (16 papers, 2007 to 2025). Infection caused by bacterial overgrowth in the vagina. "Pathogenic bacteria trigger an inflammatory response that leads to high levels of the proinflammatory cytokines IL-1β, IL-6 and IL-8, thereby causing the complications associated with bacterial vaginosis." (PMID 39479185, 2024). "Gene-environment interactions of polymorphisms for protein kinase C alpha (PRKCα), fms-like tyrosine kinase (FLT1), and IL6 with bacterial vaginosis contributed to the risk of PTB." (PMID 27766960, 2016). "Polymorphism in genes for Protein kinase C alpha (PRKCα) and IL6 interact with bacterial vaginosis and confer increased risk for PTB." (PMID 27766960, 2016). "Indeed, bacterial vaginosis has been associated with increased levels of IL-1 beta, IL-6, IL-8, IL-10 and TNF-alpha, RANTES (CCL5), macrophage inflammatory protein (MIP-1 alpha/CCL3) and MIP-1 beta (CCL4) in genital samples." (PMID 21966450, 2011). "Numerous investigations have indicated elevated concentrations of pro-inflammatory cytokines, including IL-1β, IL-6, and IL-8, in vaginal tissues from women with bacterial vaginosis (BV) relative to “healthy” controls." (PMID 39598357, 2024). "In humans, the administration of Lactobacilli vaginal tablets significantly reduces interleukin-1β (IL-1β) and (interleukin-6) IL-6 secretion in bacterial vaginosis, testifying the modulatory effects of Lactobacilli on the vaginal inflammatory response." (PMID 36986809, 2023). "HEC-1A cells were incubated separately with TNF-α, IL-1β, IL-6 or IL-8 at concentrations corresponding to the maximum levels of these cytokines determined in the cervicovaginal fluid of bacterial vaginosis patients." (PMID 36145684, 2022). "The pregnant adolescents with bacterial vaginosis had higher levels of IL-1 beta, IL-6 and IL-8 (P < 0.05)." (PMID 26465813, 2015). "Considering that adolescents are disproportionally affected by STI, the aim of this study was to evaluate the cervicovaginal levels of interleukin (IL)-1 beta, IL-6, IL-8 and bacterial sialidase in pregnant adolescents with bacterial vaginosis." (PMID 26465813, 2015). "The objective of the present study was to evaluate the cervicovaginal levels of the proinflammatory cytokines IL-1 beta, IL-6 and IL-8 and bacterial sialidase in pregnant adolescents with bacterial vaginosis." (PMID 26465813, 2015). "Pre-incubation with cranberry oil at 0.05% significantly reduced the IL-6 release by 36%, indicating that it could alleviate inflammation in the context of bacterial vaginosis." (PMID 40076798, 2025). "Previous studies reported that Atopobium vaginae could trigger an innate immune response involving IL-6 and IL-8 using an in vitro model of bacterial vaginosis, and this could be happening in vivo." (PMID 38064478, 2023). "Previous work has correlated enhanced levels of IL-1β,IL-6, MIP-1α, and MIP-2 with a higher risk of PPROM and pretermbirth.52−54 These studies demonstrate the correlation betweenbacterial infections such as bacterial vaginosis and UPEC with anupregulation of these proinflammatory markers." (PMID 37780357, 2023). "Similarly to IL-1 beta and IL-6, the IL-8 levels were higher in individuals with bacterial vaginosis (median 595.1 pg/ml; range 0.0 - 2070.0) than in those with normal flora (median 215.7 pg/ml; range 0.0 - 2358.0) (P = 0.002)." (PMID 26465813, 2015). "Not only IL-1 beta and sialidase levels, but also IL-6 and IL-8 levels are higher in pregnant adolescents with bacterial vaginosis, thus indicating that this condition elicits a more pronounced inflammatory response in this population, which potentially increases vulnerability to STI acquisition." (PMID 26465813, 2015). "We measured the relationship between bacterial vaginosis (BV) and concentrations of Interleukin-8 (IL-8), Interleukin-1β (IL-1β), and Interleukin-6 (IL-6) in cervicovaginal lavage (CVL) specimens collected longitudinally from 16 HIV-infected and 8 HIV-uninfected high-risk women." (PMID 18273408, 2007).
bacterial vaginosis (continued). "It is known that the CST IVB microbiome type in the non-pregnant state is associated with a clinical picture of bacterial vaginosis, including higher pH, increased production of proinflammatory cytokines, such as interleukin IL-6 and IL-8, and human papillomavirus (HPV) progression." (PMID 37762139, 2023). "Similarly, numerous studies have demonstrated the occurrence of high levels of cytokines and chemokines, such as IL-1β, TNF-α, IL-6 and IL-8, in vaginal fluids of women with bacterial vaginosis (BV)." (PMID 37375053, 2023). "For example, IL-1α, IL-1β, and tumor necrosis factor-α, along with bacterial vaginosis, may be associated with genetic polymorphisms in the innate immune Toll-like-receptor (TLR1, TLR 2, TLR 4 and TLR 9) and proinflammatory cytokines (IL-1β, IL-1ra, IL-6, IL-6, CXCL8, and IL-10)." (PMID 35359942, 2022). "IL-6 levels were also significantly higher in individuals with bacterial vaginosis (median 0.0 pg/ml; range 0.0 - 234.6) than in those with normal flora (median 0.0 pg/ml; range 0.0 - 100.1) (P = 0.03)." (PMID 26465813, 2015). "In this study, IL-1ß, IL-6 and IL-8 weresignificantly increased in bacterial vaginosis while TNF-α was not." (PMID 21572958, 2011). "In contrast, several studieshave shown that while IL-1ß is increased in bacterial vaginosis, IL-6 andTNF-α are not." (PMID 21572958, 2011).
dermatomyositis (16 papers, 2013 to 2025). Dermatomyositis (DM) is a type of idiopathic inflammatory myopathy characterized by evocative skin lesions and symmetrical proximal muscle weakness. "Elevated interleukin-6 (IL-6) levels have also been associated with worse clinical outcomes in patients with anti-MDA5-positive dermatomyositis and RP-ILD, further reinforcing IL-6 as a potential prognostic indicator in this subgroup." (PMID 40564181, 2025). "IL-17 is produced mainly by Th17 cells and neutrophils and correlates with dermatomyositis activity, can induce IL-6 release, and impair differentiation in myoblasts." (PMID 41488665, 2025). "In dermatomyositis, autoimmune stimuli incite the activation of alveolar macrophages, prompting the secretion of a spectrum of cytokines, including IL‐6 and IFN‐γ." (PMID 38270325, 2024). "We previously reported that dermatomyositis (DM) plasma contains a higher number of EVs than healthy controls and that EVs isolated from DM plasma triggers proinflammatory cytokines (IL-6, TNFa), including type I interferon (IFN-I) release via the STING signaling pathway." (PMID 41614843, 2025). "Researchers have also found abnormal upregulation of IFN signals and different levels of IL-6 expression in inflammatory cells and muscle fibers in dermatomyositis, tofacitinib may also alleviate the active state of dermatomyositis by significantly down-regulating the transduction pathway." (PMID 38007449, 2023). "IL-6, which has correlated with disease activity and type I IFN gene signature in dermatomyositis, was shown here to be a statistically significant independent predictor of CMAS in our JDM sera cohort." (PMID 41488665, 2025). "Considering that excessive type I interferon activity, of which most up-regulated in patients with dermatomyositis, has also been implicated in a HLH-like syndrome, targeting IL-6 alone may not be sufficient in controlling disease activity." (PMID 36131317, 2022).
Giardia infection (16 papers, 2014 to 2023). "TNF-α and IL-6 expressions are elevated during Giardia infection, their deficiency facilitates delayed elimination of the parasite." (PMID 35482821, 2022). "Dendritic cells and their importance to protective Giardia immunity has been described, as these cells are a significant source of IL-6 during Giardia infections, and infected IL-6–deficient mice have a defect in parasite clearance." (PMID 31455692, 2019). "Studies of Giardia infections in rodents have implicated interleukin-6 (IL-6) in anti-Giardia immunity." (PMID 25347704, 2014). "For example, IL-6 deficiency can significantly affect the immune response to G. duodenalis, and IL-6 can regulate B-cell maturation and induce a shift of antibody type to IgA in response to Giardia infection." (PMID 34336841, 2021). "The proinflammatory cytokines TNF-α and IL-6 are essential for the elimination and early control of giardiasis in mice." (PMID 34336841, 2021). "Previous studies of giardiasis in rodents have highlighted the essential role of IL-6 in promoting immunity against G. lamblia with elevated IL-6 mRNA levels in infected mice." (PMID 33919165, 2021). "TNF-α-deficient mice do not appear to be related to mechanisms previously shown to control Giardia infections, including IgA production, mast cell responses, IL-6 or IL-4 expression." (PMID 28979269, 2017). "Therefore, we sought to compare the effects of metronidazole and A. annua treatments on giardiasis-induced increase in IL-6 serum levels." (PMID 33919165, 2021). "In HF conditions, Giardia infection resulted in increased expression of Tnf-α (3.3-fold; p < 0.05) and Il-6 (4.2-fold; p < 0.05) compared with HF controls (Il-2 and Il-12 mRNA could not be detected in jejunal tissues)." (PMID 34552170, 2021). "Furthermore, mast cells are also involved in the control of Giardia infection through IL-6 production." (PMID 28979269, 2017). "The immune-modulating cytokine interleukin-6 (IL-6) is also involved in the control of G. lamblia infection, as IL-6-deficient mice were not able to handle the acute phase of the disease and developed chronic giardiasis." (PMID 26973630, 2016). "Additionally, mast cells can rapidly produce IL-6 to control Giardia infection in mice." (PMID 34336841, 2021). "In contrast to WT mice, IL-6-deficient mice were not able to control Giardia infection." (PMID 28979269, 2017). "Compared with the non-infected/PBS-challenged mice the Giardia-infection caused a significantly increased expression of IL-6 in the SG-competent mice, while infected SG−/− mice showed significantly reduced intestinal expression levels of IL-6 compared with infected SG+/+,+/− mice." (PMID 34335577, 2021). "It was reported that Giardia infection can enhance the production of proinflammatory cytokines, such as TNF-α, IFN-γ, IL-6, and IL-12 p40 in PMs, through the TLR2-mediated activation of MAPK signaling." (PMID 34943932, 2021). "In LF animals, no increases in Tnf-α and Il-6 were observed upon Giardia infection compared with non-infected controls." (PMID 34552170, 2021). "Furthermore, IL-6 and TNF-α are known to be involved in the elimination and early control of Giardia infection." (PMID 34336841, 2021). "Our measurement of IL-6 and TNF-α serum levels showed higher levels in infected untreated animals compared to uninfected ones, which is in line with studies which demonstrated major roles of these cytokines in controlling giardiasis." (PMID 34208266, 2021). "Untreated Giardia-infection may regulate innate and adaptive immune responses mediated by Th17 CD4+T cells and induction of Th1, Th2 and Th17 cytokines, including IL-2, IL-5, IL-6, IL-8, IL-12, IL-13, IL-23, IFN-γ and TNF-α." (PMID 30412580, 2018). "Work with mice suggests that T lymphocytes and interleukin-6 (IL-6) contribute to clearance of Giardia infection via mechanisms independent of antibodies." (PMID 25347704, 2014).
Giardia infection (continued). "The mice studied in the pertinent experiments were able to produce intestinal anti-trophozoite IgA; the findings suggest that IL-6 contributes to clearance of Giardia infection in mice (albeit by an unknown mechanism that appears not to involve IgA)." (PMID 25347704, 2014). "We found that TLR2−/− mice did not affect TNF-α and IL-6 production in vivo, while AKT-blocked mice did increase the production of these two cytokines during Giardia infection." (PMID 28979269, 2017). "AKT-blocked macrophage in vitro enhanced the production of IL-12 p40, TNF-α, and IL-6 but not IFN-γ, while the AKT inhibitor still enhanced IFN-γ production in vivo in response to Giardia infection." (PMID 28979269, 2017). "Conversely, CCL2, IL-6, LIF, and IL-12p70 levels in Giardia GS/M-infected animals treated with TcdAB were not significantly different from animals given TcdAB without giardiasis." (PMID 25289678, 2014). "In addition, macrophages from TLR2−/− mice in vitro showed enhanced production of IL-12 p40, TNF-α, and IL-6 but not IFN-γ, while TLR2−/− mice only showed enhanced production of IL-12 p40 and IFN-γ in vivo in response to Giardia infection." (PMID 28979269, 2017).
Gliosis (16 papers, 2012 to 2024). Gliosis is the focal proliferation of glial cells in the central nervous system. "Inflammatory cytokines that include IL-1, TNF-α, and IL-6 can result in gliosis, as demonstrated in the brain biopsy of seven FIRES cases." (PMID 35663267, 2022). "Gliosis following Aβ plaque stimulation releases a variety of pro-inflammatory cytokines, including IL-1β, IL-6, and TNF-α, resulting in a persistent inflammatory response." (PMID 34439569, 2021). "Gliosis with increased production of potentially harmful inflammatory mediators, including interleukin 1β (IL1β), tumour necrosis factor α (TNFα), interleukin 6 (IL6), prostanoids, and reactive oxygen species (ROS), was reported in the spinal cords of ALS patients." (PMID 30872738, 2019). "Moreover, we observed an upregulation of both IL-6 and IFN-γ in retinal lysates from untreated 3xTg-AD mice, as expression of Aβ-induced gliosis." (PMID 34611142, 2021). "A sublethal dose of LPS was shown to exacerbate depressive-like behavior, BBB disruption, and expression of interleukin-6 (IL-6) in brains of young APP23 transgenic mice vs. controls, although these mice did not yet have pre-existing plaques or gliosis." (PMID 35216491, 2022).